DHODH (dihydroorotate dehydrogenase (quinone))
Diseases named in the same sentence as DHODH in open-access papers (continued):
Sharing a sentence is not in itself a finding about the gene and the disease.
cancer (continued). "Using various databases, DHODH was identified to be commonly upregulated in various malignant tumors, including ccRCC." (PMID 38796629, 2024). "DHODH inhibitors have shown robust preclinical anticancer activity across diverse cancer types and have recently entered clinical trials for multiple hematological cancers (NCT04609826 and NCT02509052)." (PMID 38973593, 2024). "Our results demonstrate that pyrimidine nucleotide depletion by DHODH inhibition causes increased expression of APP genes and increased antigen presentation via MHC-I across a diverse panel of cancer cell lines." (PMID 37066260, 2024). "An analysis of [5-15N]glutamine metabolism has revealed that the inhibition of DHODH effectively halts nucleotide synthesis, particularly of pyrimidine nucleotides, thereby impeding cancer cell proliferation." (PMID 38921453, 2024). "Another study showed that lysyl oxidase-like 3 (LOXL3) inhibits ferroptosis and fosters chemoresistance in cancer cells by stabilizing DHODH, unveiling a regulatory mechanism in the DHODH-mediated ferroptosis defense." (PMID 38428031, 2024). "The research also delved into DHODH inhibitors, which had been known to increase ferroptosis sensitivity in cancer cells." (PMID 38206305, 2024). "High-throughput metabolic profiling has also identified DHODH inhibitors and GR agonists as key targets for regulating cancer cell metabolism, further emphasizing their relevance in cellular stress responses." (PMID 39483976, 2024). "We further explored the mechanism and functional consequences of DHODH inhibitor-mediated APP induction in cancer." (PMID 37066260, 2024). "De novo pyrimidine synthesis becomes essential during increased demands for nucleic acid precursors in rapidly dividing cells making cancer cells highly dependent on DHODH and suggesting that this enzyme is a strategic target for cancer therapy." (PMID 38577257, 2023). "The up-regulation of DHODH expression in diverse cancer types is consistent with the results from previously published data, but the effect of such up-regulation on clinical outcomes has not yet been determined." (PMID 38136273, 2023). "The combination of DHODH inhibitors with other ferroptosis-inducing therapeutic agents, such as radiotherapy and immunotherapy, has direct translational implications for cancer treatment." (PMID 37240659, 2023). "Accumulated molecular cell biology studies reveal that the inhibition of DHODH depletes intracellular pyrimidine nucleotide pools, thereby leading to cell cycle arrest and sensitization to current chemotherapies in cancer cells." (PMID 36672495, 2023). "In parallel to the differential expression of DHODH in different cancers, the therapeutic efficacy of DHODH inhibition also varies." (PMID 36672495, 2023). "Although functional studies characterized DHODH as a potential target for treating cancer, several potent DHODH suppressors such as brequinar, leflunomide, and teriflunomide were clinically assessed but failed to receive FDA approval." (PMID 37735472, 2023). "In summary, DHODH-mediated ferroptosis in cancer is expected to become a new target for tumor therapy, and a nano-platform based on DHODH inhibitors has been reported to block the redox system." (PMID 36970345, 2023). "FSP1 and DHODH play a role in preventing ferroptosis, implicating them as promising targets for cancer therapy, particularly in cancers with relatively less functioning of the core ferroptosis regulatory system, xCT/GSH/GPX4." (PMID 37371948, 2023). "The inactivation of DHODH sensitizes GPX4-high cancer cells to ferroptosis inducers and enhances ferroptosis in GPX4-low cancer cells." (PMID 37762411, 2023). "DHODH has been extensively analyzed as a potential target for cancer therapy due to the increased demand for nucleotides by rapidly proliferating cells." (PMID 37762411, 2023). "The specific DHODH inhibitor brequinar selectively suppresses cancer cells with low expression of GPX4 induced tumor growth." (PMID 35882850, 2022).
cancer (continued). "DHODH inhibitors have therapeutic effects against several diseases, such as malaria, autoimmune diseases, cancer, and myeloid malignancies." (PMID 36412986, 2022). "Overexpression of DHODH is observed in various cancers, and DHODH acts as an oncogene in some cancer types." (PMID 35629914, 2022). "DHODH is over-expressed in cancer cells and is integral for promoting cell proliferation through pyrimidine biosynthesis and H2O2 signaling." (PMID 36611901, 2022). "As an iron-containing flavin-dependent enzyme, DHODH couples the pyrimidine biosynthesis pathway to the mitochondrial respiratory chain, suggesting possible strategies for treating GPX4low cancers by targeting DHODH." (PMID 35075250, 2022). "As dihydroorotate dehydrogenase (DHODH) converts dihydroorotate to orotate in UMP de novo synthesis and antitumor properties were observed in several cancer tissues, the focus shifted towards DHODH as a target in cancer therapy." (PMID 35203388, 2022). "Lef, as the inhibitor of DHODH, has been reported by several pre-clinical studies to exert an antitumor effect on several types of cancers." (PMID 35169125, 2022). "Second, even though the direct contribution of DhoDH to ATP generation is only marginal in various cancer cells at baseline (5–10% of routine respiration, coupled with ATP production), it can vary depending on conditions." (PMID 35448547, 2022). "The modulation of DHODH activity in cancer focused on activating the biosynthesis of de novo pyrimidine biosynthesis through CAD complex." (PMID 36524129, 2022). "Studies employing cell bypassing coenzyme Q oxidation have suggested that the only essential function of the ETS for the growth of some cancer cells is to preserve DhoDH activity, emphasizing the importance of this pathway when conditions change." (PMID 35448547, 2022). "In recent years, multiple studies in different cancer cell and animal models, as well as patient-derived cancer cells and xenograft models, once again elucidated the importance of targeting DHODH alone or in combination with other anti-cancer agents." (PMID 35203388, 2022). "Initially used to treat rheumatoid arthritis and multiple sclerosis, DHODH inhibitors were later found helpful in treating cancer, viral infections, and blood disorders." (PMID 36309489, 2022). "Initially, in different types of cancer cells, lipid peroxidation drives the synthesis of pyrimidine bases in the presence of a specific enzyme dihydroorotate dehydrogenase (DHODH) located on mitochondria." (PMID 35402247, 2022). "Previous results have suggested that DHODH suppression was correlated with decreased cell proliferation in most cancer cell lines, which was consistent with it being a poor prognostic factor in our result." (PMID 36524129, 2022). "Nevertheless, these findings together suggest that a combination of targeting DHODH and nucleoside transport is a promising treatment strategy for both pediatric and adult cancers." (PMID 34462431, 2021). "Celastrol, extracted from “Thunder of God Vine,” is a DHODH inhibitor and promising anti-cancer natural product." (PMID 33971967, 2021). "Studies verify that combination of DHODH inhibitors with traditional cell toxicity anti-cancer drugs synergistically inhibits tumor proliferation." (PMID 33971967, 2021). "Collectively, we detailly discuss the association between DHODH and tumors in recent years here, and believe it will provide significant evidences and potential strategies for utilizing DHODH as a potential target in preclinical and clinical cancer therapies." (PMID 33971967, 2021). "In 1959, its role in tumor progression was first reported, and increasing evidences indicated that DHODH expression and activity are directly related to cancer progression." (PMID 33971967, 2021).
cancer (continued). "In 2016, a series of compounds inducing pyrimidine depletion, i.e., DHODH inhibitors, were found to promote differentiation in several AML models, underlying the wide influence of metabolism on cancer cells’ behavior." (PMID 33670894, 2021). "Since then, considerable effort has been invested in developing DHODH inhibitors and determining their efficacy as well as their anti-cancer and anti-viral potential." (PMID 34145214, 2021). "The broad-ranging progresses in recent years made in DHODH inhibitor development for cancer therapy are summarized." (PMID 33971967, 2021). "Considering that cancer cells frequently hijack nucleotide metabolism to boost cell proliferation, we examined the role of DHODH in cellular de novo pyrimidine synthesis in OSCC cells." (PMID 33510132, 2021). "Cancer cells are hypersensitive to DHODH inhibitors under the tumor hypoxia and nutrient-deprived microenvironment." (PMID 33971967, 2021). "Taken together, DHODH is releasing increasing potential abilities in various cancer therapies and it is worthy of expecting its more powerful utilization in other tumors." (PMID 33971967, 2021). "The functional or biochemical role of DHODH in cancers or other diseases’ development as well as of their related inhibitors has been well reviewed in several papers." (PMID 33971967, 2021). "The relationship of DHODH with de novo pyrimidine metabolism and mitochondria system in various cancers is discussed." (PMID 33971967, 2021). "The last example of an electrostatically associated peripheral membrane protein is the enzyme dihydroorotate dehydrogenase (DHODH), which has been revealed as a potential target in the fight against cancer." (PMID 34066904, 2021). "Targeting CAD or the critical downstream enzyme DHODH via alleviating carbon influx through pyrimidine synthesis inhibited cancer cell survival, self-renewal." (PMID 34638594, 2021). "Due to an increased demand for nucleotides in rapidly proliferating cells, DHODH has been intensively explored as a promising target for cancer therapy during the past years." (PMID 34611144, 2021). "DHODH in the inner mitochondrial membrane inhibits lipid peroxidation in the mitochondria by reducing CoQ10 to CoQ10H2, indicating that DHODH can be a novel therapeutic target in cancer therapy by inducing ferroptosis." (PMID 34912804, 2021). "Depletion of pyrimidine ribonucleotide pools is thought to be the main reason why DHODH inhibitors reduce RNA virus replication and slow down the proliferation of fast-growing cells such as activated T cells and cancer cells." (PMID 34113829, 2021). "For example, when cells are treated with anti-cancer agent fenretinide which can induce ROS production, DHODH suppression significantly reduces fenretinide-induced ROS generation." (PMID 33971967, 2021). "Taken together, the connection between DHODH and ROS in cancer is not fully understood and remains to be further verified." (PMID 33971967, 2021). "There has been a renewed interest in DHODH inhibitors as cancer therapeutics in light of recent laboratory findings." (PMID 34462431, 2021). "The DHODH inhibitor BRQ was explored as a cancer-therapeutic agent with promising data from animal studies." (PMID 34462431, 2021). "In this review, we mainly unravel the biological function of DHODH in tumor progression, including its crucial role in de novo pyrimidine synthesis and mitochondrial respiratory chain in cancer cells." (PMID 33971967, 2021). "Our findings add to the knowledge of how cancer cells co-opt nucleotide metabolism to support their rapid growth, and thereby highlight DHODH as a potential prognostic and therapeutic target for OSCC treatment." (PMID 33510132, 2021). "A way to increase the efficacy of DHODH inhibitors against cancer cells is to combine them with other agents." (PMID 33020720, 2020).
cancer (continued). "The recent advances in the identification of small molecule modulators of pyrimidine ribonucleotide synthesis, and in particular of small molecule inhibitors of DHODH, have led to a renewed interest in this field of research for the treatment of cancer." (PMID 33020720, 2020). "Recent studies targeting DHODH or IMPDH reveal metabolic vulnerabilities potentially exploitable in cancer treatment." (PMID 31108873, 2019). "Targeting cancer metabolism through the inhibition of DHODH has recently received much consideration." (PMID 31108873, 2019). "As the rate-limiting enzyme in pyrimidine biosynthesis, DHODH is now becoming an attractive target for anti-cancer therapy." (PMID 31551419, 2019). "In human, DHODH has been validated as a potential target for treating a variety of autoimmune disease as well as cancer." (PMID 30200251, 2018). "The inhibition of pyrimidine biosynthesis is a strategy used to treat various diseases, such as cancer, immunological disorders and infections, and the development of DHODH inhibitors has been under continuous investigation." (PMID 30459406, 2018). "Leflunomide is also reported to be able to effectively reduce cell growth and proliferation by inhibiting DHODH activity in several types of cancers." (PMID 30200251, 2018). "Beside the novel synthetic lethality revealed by this study, our work also further highlights the relevance of targeting DHODH in cancer." (PMID 29221122, 2017). "Altogether these data confirmed that combining IC10 Chk1 inhibitor with a DHODH inhibitor can convert two cytostatic effects into cytotoxicity in both mouse and human cancer cells in culture." (PMID 29221122, 2017). "Reduction in nucleotide pools through the inhibition of mitochondrial enzyme dihydroorotate dehydrogenase (DHODH) has been demonstrated to effectively reduce cancer cell proliferation and tumour growth." (PMID 29221122, 2017). "DHODH inhibition also effectively slowed down cancer cell and tumour growth of diverse tissue origins." (PMID 29221122, 2017). "The results are in good agreement with data indicating that the DHODH inhibitorleflunomide/teriflunomide induces apoptosis in a number of human cancer celllines." (PMID 24772329, 2014). "One explanation for this is the stringent species specificity of these drugs (which target the Plasmodium ortholog), since one DHODH inhibitor, brequinar, did show (modest) efficacy in cancer." (PMID 24391728, 2013). "In cancer, DHODH is thought to mitigate ROS accumulation, enabling evasion of apoptosis." (PMID 41549155, 2026). "In mouse models, DHODH inhibition enhances the efficacy of immune checkpoint blockade using anti-CTLA-4 with anti-PD-1 antibodies by up-regulating the expression of antigen presentation pathway genes in cancer cells." (PMID 40519286, 2025). "In addition to promoting nucleotide synthesis, DHODH activity strengthens cancer cells by providing defense against ferroptosis." (PMID 40519286, 2025). "DHODH inhibitors are in clinical trials to treat a series of different cancer types." (PMID 40961924, 2025). "Consequently, some researchers propose DHODH as a potential therapeutic target for oxidative phosphorylation-dependent cancers." (PMID 40289989, 2025). "Moreover, multiple GPX4-independent antioxidant enzymes, such as apoptosis-inducing factor mitochondria-associated 2 (AIFM2, also known as FSP1) and dihydroorotate dehydrogenase (DHODH), inhibit ferroptosis in cancer cells with low GPX4 expression." (PMID 39534872, 2024). "Notably, the role of DHODH in inducing ferroptosis in cancer cells suggests an additional therapeutic angle." (PMID 39697237, 2024).
cancer (continued). "Although there is a vast literature on DHODH inhibitors dating back to the early 1990s, and despite the “rediscovery” of DHODH in recent years as a critical cancer cell metabolic dependency, important questions about the cellular response to DHODH inhibition remain unanswered." (PMID 37066260, 2024). "explored that DHODH inhibitors, particularly the high concentration of Brequinar, could sensitize cancer cells to ferroptosis by inhibiting FSP1." (PMID 38414669, 2024). "Furthermore, the combined inhibition of GPX4 and mitochondrial dihydroorotate dehydrogenase (DHODH) effectively eradicated GPX4high cancer cells, highlighting the synergistic induction of ferroptosis resistance by GPX4 and DHODH." (PMID 39061847, 2024). "Therefore, the addition of a DHODH inhibitor such as breqinar increases sensitivity to ferroptosis in the inner mitochondrial membrane, and the inactivation of DHODH induces widespread ferroptosis in cancer cells with low GPX4 expression." (PMID 38511140, 2024). "Inhibition of DHODH induces ferroptosis in cancer cells, suggesting a new therapeutic angle." (PMID 39697237, 2024). "DHODH is an inner mitochondrial membrane enzyme, an enzyme essential for the de novo biosynthesis of pyrimidine-based nucleotides, which catalyzes the de novo synthesis of pyrimidine ribonucleotide and crucially affects the metabolism of cancer cells." (PMID 37762411, 2023). "DHODH plays a critical role in promoting cancer cell proliferation, which may be a highly sensitive target to inhibit nucleotide synthesis." (PMID 38136273, 2023). "DHODH inhibition that depletes pyrimidine ribonucleotides is also thought to be responsible for reduced RNA virus replication and decelerated growth in rapidly dividing cells, such as activated T cells and, as just mentioned, cancer cells." (PMID 38577257, 2023). "Highly proliferative cells (such as cancer or pluripotent cells) share a similar preference depending on the de novo pathway for pyrimidine biosynthesis, which is regulated by the rate-limiting DHODH." (PMID 36814599, 2023). "Indeed, the determined tumorigenic role of DHODH has led to numerous attempts to develop DHODH inhibitors for cancer treatment." (PMID 36672495, 2023). "Therefore, drugging DHODH has increasingly been proposed as part of combination therapies in cancer treatment." (PMID 36672495, 2023). "We first detected LOXL3-S704 phosphorylation, and AK2 and DHODH protein levels, in the cancer and adjacent tissues of these 50 HCC patients, using the indicated antibodies with the first validating their specificity: LOXL3-S704 phosphorylation was significantly upregulated in the human HCC tissue." (PMID 37253718, 2023). "Our results could identify the overexpression of DHODH in selected types of cancer as a target or prognostic factor to better forecast potential outcomes and to determine which patients merit more aggressive therapeutic measures." (PMID 38136273, 2023). "Emerging reports imply that DHODH is a potential target for cancer therapy." (PMID 38136273, 2023). "Sulfasalazine can inhibit system xc, so the combination of DHODH inhibitors and sulfasalazine may become a new strategy for cancer treatment." (PMID 36309489, 2022). "Potent DHODH inhibitors are sensitive to cancer cell lines with low GPX4 expression levels." (PMID 35402247, 2022). "Similarly, the inner mitochondria membrane-localized enzyme, dihydroorotate dehydrogenase (DHODH), was shown to modulate ferroptosis sensitivity wherein the deletion or inhibition of the enzyme promoted or sensitized cancer cells to ferroptosis." (PMID 35065965, 2022). "Provided that DHODH is a critical target for drugs against cancer, knowledge of this mechanism could ultimately prove fundamental to applications in DHODH-targeted therapy." (PMID 34066904, 2021). "Taken together, DHODH inhibitors and anti-cancer drug combination may be a promising method of cancer therapy." (PMID 33971967, 2021).